CRP (C-reactive protein)
Diseases named in the same sentence as CRP in open-access papers (continued):
Sharing a sentence is not in itself a finding about the gene and the disease.
diabetes (continued). "Advanced age, active smoking, comorbidity, especially hypertension, diabetes, arrhythmia, CAD and neutrophil, CRP, LDH, D-dimer and AST levels were associated with mortality." (PMID 34485485, 2020). "Prior studies have found an association between SO and functionality, sedentarism, biomarkers such as C-reactive protein (CRP), glucose, and albumin, and diabetes mellitus." (PMID 33263630, 2020). "There was evidence of publication bias in both funnel plot asymmetry and Egger’s test for cough, unspecified comorbidity, cardiovascular disease, hypertension, malignancy, diabetes, haemoglobin, prothrombin time, urea nitrogen and C-reactive protein." (PMID 33141836, 2020). "In the stepwise analysis, covariant factors included hypertension, diabetes mellitus, hs-CRP, LDL-C, smoking, triglycerides, WBC, and IL-6." (PMID 32652935, 2020). "This study is aimed at exploring the relationship between serum ferritin and blood lipids and the influence of diabetes and different hs-CRP levels." (PMID 32280714, 2020). "In non-obese participants, increasing age, male sex, hypertension, diabetes, abdominal obesity, eGFR (P < 0.001), CRP (P = 0.001), current smoking, AST, ALT, and γ-GT levels (P < 0.001) were significantly associated with CAC." (PMID 31974458, 2020). "Patients with higher galectin-1 concentrations were older; had greater prevalence of hypertension, diabetes, chronic kidney disease, and heart failure; and were more likely to present with higher hs-CRP levels and SYNTAX scores." (PMID 33244142, 2020). "The first source includes factors such as smoking, hypertension, hyperlipidemia, atrial fibrillation, diabetes mellitus, C-reactive protein (>5 mg/l), and coronary artery disease." (PMID 33329364, 2020). "This association was evidenced by multiple stepwise regression analysis of variables that were independently associated with serum levels of CXCL16 including decreased eGFR, diabetes mellitus, hypertension, increased CRP and PTH levels." (PMID 33312065, 2020). "Fluoroquinolone-containing regimens were more likely selected for patients with cavitary lesions, diabetes mellitus, culture negativity, a low daily physical activity level, a decreased lymphocyte count and an increased CRP level." (PMID 32645105, 2020). "Our study confirmed previously reported prognosticators, including age, male gender, hypertension, diabetes, active smoking, increased CRP, and elevated D-dimer levels." (PMID 33326457, 2020). "The frequency of severe cases was higher in diabetes patients that showed higher concentrations of C-reactive protein (CRP), lactate dehydrogenase (LDH) and IL-6, lower CD4/CD8 cell ratio compared to other two groups." (PMID 33584667, 2020). "Apart from uric acid indicators, other clinical parameters such as age, ratio of hypertension, ratio of diabetes, HB, CRP, ALB, LDL, HDL, TC, BUN, Scr, Ucr, and Ccr were all significantly different among groups." (PMID 32698778, 2020). "After adjusting for age, dialysis vintage, education, diabetes, serum albumin, hs-CRP, hyponatremia and mean arterial pressure, total Kt/V was only independently associated with delayed memory (P = 0.015)." (PMID 31643008, 2020). "The following variables were initially evaluated: age (>65 years), clinical severity of ischemic stroke (NIHSS score ≥8), presence of hypertension, presence of diabetes mellitus, C reactive protein levels, presence of arterial stiffness (ASI > 0.70)." (PMID 32849200, 2020). "Among the factors with high consistency of association, we found age, C-reactive protein, D-dimer, albumin, body temperature, SOFA score and diabetes." (PMID 32491116, 2020). "Increase in AG positively correlated with a high CRP level, but negatively correlated with comorbid diabetes." (PMID 33019590, 2020). "Higher CRP concentration was also associated with higher odds of PAD and nephropathy in non-diabetes and higher odds of PAD in diabetes." (PMID 32665312, 2020).
diabetes (continued). "In unadjusted analysis, age, diabetes mellitus, undergoing surgery for cancer, minimal vs. open surgery, having any complication, and CRP were significantly related to the NRS on any postoperative day." (PMID 32318795, 2020). "The level of HbA1c of patients with diabetes was in a positive correlation with blood pressure and level of hs-CRP." (PMID 31086532, 2019). "The results were similar (OR: 6.925; 95% CI: 4.15-11.375; P < 0.001) when we conducted the analysis after adjusted for age, gender, hypertension, diabetes mellitus, smoking habit, hs-cTnT, CK-MB, hs-CRP, NT-proBNP, and BMI." (PMID 31523180, 2019). "Selected variables included age, sex, employment status, income, education level, nutritional factor (high-sensitivity C-reactive protein and albumin), diabetes mellitus, severe anemia, basal serum creatinine, and proteinuria." (PMID 31863079, 2019). "What has to be emphasized is that some clinical conditions have been previously identified as related to complicated AA, such as the co-existence of diabetes mellitus, elevated CRP, and leukocytosis." (PMID 31616053, 2019). "Multivariate analysis confirmed that UAPN concentrations remained independently predictor of CIN after adjusted for diabetes mellitus, Scr, contrast use and hs-CRP." (PMID 31269899, 2019). "Higher SAF was significantly related to lower 25(OH)D3, lower eGFR, male sex, higher age, BMI and CRP, more coffee consumption, current smoker, diabetes, use of more medications, and longer time interval between measurements." (PMID 30255328, 2019). "Given the known association between higher Cyr61 levels and STEMI, we adjusted for STEMI and other risk factors including age, gender, BMI, hypertension, diabetes, LDL cholesterol, LVEF, troponin T, STEMI and serum creatinine and CRP." (PMID 31672144, 2019). "Lipid profile (total cholesterol, LDL, HDL, and triglycerides), inflammation (hs-CRP), progression to type 2 diabetes mellitus, as well as safety indices (ALT, AST) will be obtained." (PMID 30616613, 2019). "Measures for smoking, BMI, diabetes and hypertension were added separately and together to establish their individual and joint attenuating effects on the SEP/CRP association." (PMID 30692559, 2019). "The combined group was associated with higher prevalence of diabetes mellitus, higher WBC and CRP, less revascularization, and lower Hb compared to the NTIS, the renal dysfunction and the normal group after controlling for age and sex (all P < 0.05)." (PMID 30832591, 2019). "Neither have there been any studies that have investigated the relationship between CRP and incident diabetes in a large population-based Korean cohort." (PMID 30872696, 2019). "The pattern of increases in CRP with indications for diabetes and hypertension are more mixed with consistent, significant differences in Whitehall II and ELSA but not in the other studies." (PMID 30692559, 2019). "Levels of SFRP5 are lower in individuals with obesity, diabetes, non-alcoholic fatty liver disease, and hypertension and negatively correlated with C-reactive protein (CRP)." (PMID 30915034, 2019). "Data on diabetes bacteremia were quantitative used blood glucose levels, the bacterial count, and C-reactive protein (CRP) and were analyzed using the one-way analysis of variance test with a confidence level of 95%." (PMID 31440004, 2019). "For the development of AKI, the AUC of a multivariable model, including positive inotrope support, a history of diabetes mellitus, and CRP, was 0.693 (95% CI: 0.626–0.760, p < 0.001)." (PMID 30971264, 2019). "A meta-analysis of mostly cross-sectional studies relating CRP to cardiovascular disease risk factors showed strong correlations between elevated levels of CRP and diabetes, hypertension, and dyslipidemia." (PMID 29462285, 2019).
diabetes (continued). "We created a model that included six predictors of AKI: four (history of diabetes, BUN to creatinine ratio, CRP, and osteopontin) had a positive association with AKI risk; while two (CD5 antigen‐like and Factor VII) had a negative association with AKI risk." (PMID 30582197, 2019). "In the present work, we also observed correlations between GDF8 levels and traditional cardiovascular risk factors such as diabetes, increased systolic and diastolic blood pressure, increased LDL cholesterol and CRP." (PMID 31906236, 2019). "Male sex, obesity, diabetes, and plasma levels of cystatin C, GDF‐15, and CRP‐hs were independently associated with higher IL‐18 levels." (PMID 31596518, 2019). "Existing clinical data indicate that diabetes, as a whole, is strongly associated with elevated levels of IL-6, TNF-α, CRP, and adiponectin in Mexican Americans." (PMID 30868076, 2019). "The variables significantly associated with increasing IL‐18 concentration at baseline were male sex, age, diabetes, BMI > 30 kg/m2 and increasing levels of the biomarkers NT‐proBNP, cTnT‐hs, CRP‐hs, and cystatin C." (PMID 31596518, 2019). "Drugs that reduce CRP concentrations effectively inhibit atherosclerosis progress, especially in patients with diabetes or IR." (PMID 31208420, 2019). "Consistent with previous reports that plasma CRP is a predictor of diabetes, plasma CRP levels in our subjects were elevated in diabetic patients compared to nondiabetic controls." (PMID 30868076, 2019). "Age, gender, smoking status, and systolic blood pressure are included in all risk equations, but cholesterol (total or LDL or HDL cholesterol), diabetes mellitus status, family history, antihypertensive therapy, HbA1c and CRP are only used in part of them." (PMID 30705337, 2019). "Numerous investigations have proven that serum hypersensitive C-reactive protein (hsCRP) concentration in patients with type 2 diabetes mellitus (T2DM) is increased." (PMID 31281843, 2019). "Vitamin D supplementation in patients with diabetes mellitus type 2 helps decrease C-reactive protein and TNF-alpha concentrations, decrease ESR, and increase leptin concentrations." (PMID 30881343, 2019). "Many studies have shown that proinflammatory cytokines including TNF-α, IL-6, IL-1β, CRP, and NF-κB can lead to IR and the development of related diseases such as metabolic syndrome and diabetes, either alone or in combination, via various pathways." (PMID 31218568, 2019). "Multivariate analysis of 6-h lactate normalization adjusted for age, sex, past medical history of diabetes and malignancy, pulse rate, hemoglobin, creatinine, aspartate transaminase, C-reactive protein and SOFA score which had p<0.05 in univariate analysis." (PMID 31158247, 2019). "In this study, hs-CRP, miR-21, and diabetes (VIP > 1) were highly correlated with the maximum area of lipid core, the number of vessels, the number of macrophages, the thickness of the fibrous cap and the number of vulnerable plaques." (PMID 31764830, 2019). "By including HbA1c, C reactive protein, and the number of medications, the model became a perfect predictor for diabetes remission." (PMID 31344893, 2019). "Moreover, elevated CRP levels have been shown to be associated with coronary heart disease, cancer, inflammatory diseases, respiratory disorders, chronic kidney disease, bacterial or viral infections, diabetes, obesity, metabolic syndrome, psychiatric problems, depression, and other diseases." (PMID 30728031, 2019). "The association between calcidiol/paricalcitol treatment and elevated mortality remained significant after adjusting for age, sex, diabetes, C-reactive protein, and hemodialysis vintage." (PMID 31035488, 2019). "There was no statistical difference between the two groups regarding the prevalence of diabetes mellitus or metabolic syndrome and values of hs-CRP, body mass index, blood glucose, and triglycerides." (PMID 31320839, 2019).
diabetes (continued). "Factors found to be associated with more blood culture sampling in multivariate analysis were diabetes, duration of symptoms shorter than 2 days and higher C-reactive protein (CRP) level." (PMID 31011854, 2019). "Age, sex, diabetes type, HbA1c level, CRP, osteomyelitis, vasculopathy, neuropathy, response to antibacterial therapy, wound characteristics, treatment types and results, and bacteriology and mycology of the ulcers were summarized in Table." (PMID 30761877, 2019). "The high-BRS group had a significantly higher rate of smoking and significantly lower diabetes prevalence, intimal thickness, C-reactive protein, and glycosylated hemoglobin (HbA1c) levels compared to the low-BRS group." (PMID 30832391, 2019). "These were used with UAE and derived measures of HDL apoA-I content (apoA-I/HDL-C and apoA-I/HDL-P) in risk models adjusted for gender, age, apoB, diabetes, past CVD history, CRP and GFR." (PMID 30813431, 2019). "The area under the curve (AUC) of the multivariable model, including positive inotrope support, a history of diabetes mellitus, and CRP, was 0.693 (95% CI: 0.626–0.760, p < 0.001) in predicting AKIN." (PMID 30971264, 2019). "Compared with patients without CKD, those with CKD were of older age, included more males and those with diabetes, had lower hemoglobin levels, and higher blood urea nitrogen, serum creatinine, C-reactive protein (CRP), and potassium levels." (PMID 31186488, 2019). "We showed that a steady increase in CRP over time was associated with subsequent hypertension, low HDL-cholesterol, and obesity, and maintaining high levels of CRP was associated with diabetes and obesity." (PMID 29462285, 2019). "Elevation of PAr in patients with diabetes was mostly explained by levels of renal function markers and CRP." (PMID 30845778, 2019). "The following data were collected at the time of catheter implantation: CRP-value, history of catheter-related infection, microbiological status, immunosuppression and diabetes mellitus." (PMID 31151433, 2019). "Elevated circulating levels of CRP have been observed in several diseases related to IR, such as type 2 diabetes mellitus (T2DM), atherosclerosis, cardiovascular disease, and metabolic syndrome." (PMID 31983920, 2019). "Diabetes and higher CRP provoked clinicians to order blood culture sampling in accordance with data in erysipelas and uncomplicated cellulitis." (PMID 31011854, 2019). "Multivariate linear regression was performed to study the interaction of PTX3 with age, gender, smoking history, family history of cerebrovascular disease, BMI, level of TNF-α, CHOL, TG, HDL, hs-CRP, hypertension, diabetes mellitus, and history of statin use." (PMID 31998222, 2019). "The International Diabetes Federation suggested that pro-inflammatory states including rises in levels of high-sensitivity CRP and cytokines, as well as a decrease in plasma adiponectin levels, needed to be added to clinical metabolic parameters of MetS." (PMID 29382113, 2018). "For example, in a Mendelian randomisation study no causal links were found between IL-1 receptor antagonist (IL-1Ra) or C-reactive protein (CRP) and diabetes-related outcomes, while IL-1Ra is associated with 2 h glucose and insulin sensitivity." (PMID 29159468, 2018). "The odds ratio of patients with the high CD8+ TEMRA and high intermediate monocyte immunophenotype for CAD and CVD is higher than every 1 mg/dL increase in high-sensitivity CRP and is in a range close to diabetes." (PMID 30455721, 2018). "We previously reported a linear relationship between UA and endothelial dysfunction and, subsequently, we also observed that both high sensitivity C-reactive protein concentrations and impaired endothelial function are independent predictors of new diabetes." (PMID 29619007, 2018).
diabetes (continued). "In the logistic regression analysis, BMI, sex, age, high blood pressure, diabetes, HbA1c, high uric acid hematic disease, hs-CRP, levels of ALT, AST, TC, TG, LDL, and HDL, and NAFLD were independent variables, and sarcopenia was the dependent variable." (PMID 29785395, 2018). "Observed difference in CRP at baseline remained significant following adjustment (p<0.01) for age, gender, BMI, diabetes and therapy with statins at baseline." (PMID 30540752, 2018). "Diabetes usually results in higher levels of hs-CRP and lower levels of 25(OH)D concentrations suggesting a larger effect size in subjects with this condition." (PMID 30050908, 2018). "The ORs of age (95% CI: 1.04-1.06, p < 0.001), family history of diabetes (95% CI: 2.5-3.16, p < 0.001), and hs-CRP (95% CI: 1.01-1.02, p < 0.001) were 1.05, 2.81, 1.02, respectively." (PMID 29374085, 2018). "In the ECLIPSE cohort, most COPD patients with heart disease had elevated IL-6, IL-8, and fibrinogen, while those with hypertension had elevated fibrinogen and those with diabetes had elevated CRP." (PMID 29720140, 2018). "Elevated CRP was identified as a predictor of metabolic syndrome independently of diabetes mellitus in family history, BMI > 25 kg/m2, and hyperlipidemia in family history (p = 0.042)." (PMID 30190688, 2018). "In the subsequent analysis of the relationship between CRP and type 1 diabetes mellitus (T1DM), the pooled result (OR 1.017145; 95% CI 0.9066489 to 1.14225; P = 0.909) supported that CRP levels cannot determine the risk of developing T1DM." (PMID 30619477, 2018). "Diastolic blood pressure, systolic blood pressure, high-density lipoprotein, low-density lipoprotein, body mass index and hyper-sensitive C-reactive protein were higher in diabetes combined with hyperlipidemia group than in diabetes group (P < 0.05)." (PMID 29739462, 2018). "Previous studies have demonstrated that CAC was associated with age, sex, glucose level, high-density lipoprotein (HDL)-cholesterol level, LDL-cholesterol level, triglyceride level, body mass index (BMI), diabetes mellitus, and C-reactive protein (CRP) level." (PMID 30226851, 2018). "Serum high-sensitive CRP level was higher in patients with diabetes (P = 0.003) and max IMT was lower in patients with PA (P = 0.024)." (PMID 29715313, 2018). "The association was still significant after further controlling for smoking status; alcohol drinking; CRP; and family history of diabetes, hypertension, and CAD." (PMID 30568717, 2018). "Some of these conceptions considered CRP POCT as a test for specific diseases such as diabetes or as a general comprehensive blood test to detect any disease in humans." (PMID 29633689, 2018). "Further controlling for smoking status; alcohol drinking; CRP; and family history of diabetes, hypertension, and CAD only slightly attenuated the strength of the association for MetS, central obesity, and hypertriglyceridemia." (PMID 30568717, 2018). "Low HSP27 patients were older, had higher left ventricular mass index, lower ejection fraction, higher prevalence of diabetes, myocardial infarction and carotid atherosclerosis, higher C-reactive protein level, and worse oxidant/antioxidant status." (PMID 30558560, 2018). "WL subjects had a significantly higher burden of age, SBP, PBG, CRP, diabetes mellitus, and hypertension compared with WOL subjects, whereas TC and ApoA I levels were lower in WL compared with those in WOL patients (P<0.05)." (PMID 29896432, 2018). "In women, obesity, inflammation (high CRP), insufficient sleep, and family history of diabetes or heart attack increased the likelihood of frailty, suggesting a high-stress burden." (PMID 29507821, 2018). "Frailty was more likely in women who were obese, had elevated CRP indicating inflammation, were physically inactive, slept less than 6 h, were hospitalized previously and had a family history of diabetes or heart attack." (PMID 29507821, 2018).